HMMR (hyaluronan mediated motility receptor)
Diseases named in the same sentence as HMMR in open-access papers (continued):
Sharing a sentence is not in itself a finding about the gene and the disease.
tumor (160 papers, 2006 to 2026). "In cancer, HMMR overexpression has been associated with increased tumor aggressiveness and metastasis, as it activates several signaling pathways, including MAPK and PI3K/Akt, that drive cell growth and survival." (PMID 40567905, 2025). "Increased HMMR expression has been associated with poor prognosis, as it promotes tumor growth and metastasis." (PMID 41154660, 2025). "HMMR, a protein essential for cell division and a known promoter of tumor development, has been implicated in targeting FAM83D to the mitotic spindle." (PMID 40567905, 2025). "By disrupting this pathway, not only can we target HMMR but also modulate its associated genes, presenting a comprehensive approach to curb tumor growth." (PMID 38576486, 2024). "According to several research, increased HMMR expression is linked to a bad prognosis because it speeds up tumor growth and metastasis." (PMID 36750807, 2023). "For most tumor types, high HMMR expression was associated with reduced Overall Survival (OS), Return to Functional Status (RFS), and Platinum Free Interval (PFI)." (PMID 36704516, 2022). "Three membrane-associated proteins, namely E-selectin, BST2, and HMMR were found to be upregulated in LECs after direct interaction with highly metastatic tumor cells." (PMID 31963450, 2020). "In particular, HMMR, a cell surface hyaluronan receptor and mitotic spindle protein and the driver of tumor progression, has been implicated in the targeting of FAM83D to the mitotic spindle." (PMID 29088801, 2017). "Higher HMMR expression associated strongly with increased INSS tumour grade." (PMID 41253884, 2025). "In current study, we hypothesize that hsa-let-7c-5p may serve as a potential regulator of HMMR expression, which was down-regulated in tumour tissues and associated with a favourable prognosis." (PMID 38633247, 2024). "Additionally, our previous study found that HMMR was elevated in PCa tumours tissues and associated with poor prognosis." (PMID 36750558, 2023). "Furthermore, the overexpression of HMMR in numerous tumor types is also associated with tumor relapse and propagation." (PMID 33403045, 2021). "Considering that HMMR can be considered a tumor-associated antigen, immunotherapy with the HMMR protein could be a novel strategy." (PMID 33763352, 2021). "Furthermore, these investigations imply that HMMR is linked to tumor growth and metastasis." (PMID 36750807, 2023). "HMMR rs299290 could also influence expression of neighboring genes and, thereby, combined deregulation of HMMR and other gene products might further affect the risk outcome and tumor features." (PMID 35393420, 2022). "Here, we investigated whether we could introduce the receptor for hyaluronic acid-mediated motility (RHAMM/HMMR/CD168), another clinically relevant tumor-associated antigen, into these mo-DCs through mRNA electroporation and elicit RHAMM-specific immune responses." (PMID 27659531, 2016). "To elucidate the mechanism by which HMMR facilitates tumor metastasis, we conducted mRNA sequencing and mass spectrometry, identifying MAP4K4 as a key protein that interacts with and is regulated by HMMR." (PMID 39990663, 2025). "Mechanistically, HMMR promotes tumor metastasis by binding to mitogen-activated protein kinase kinase kinase kinase 4 (MAP4K4), which activates the p-JNK/p-c-JUN/MMP1 signaling cascade." (PMID 39990663, 2025). "Using xenografted tumours of our KELLY derivatives, our study supports the possibility that HMMR positively promotes KELLY tumour growth." (PMID 41253884, 2025). "The survival of mice harboring HMMR-deficient KA5 and KA14 tumors was significantly prolonged compared to parental KELLY, corroborating the tumour-supporting role of HMMR." (PMID 41253884, 2025). "Mechanistically, HMMR promotes tumor metastasis by interacting with MAP4K4, which in turn activates the p-JNK/p-c-JUN/MMP1 signaling pathway." (PMID 39990663, 2025).
tumor (continued). "HMMR knockdown inhibited tumor cell migration and invasion, while its overexpression enhanced these processes." (PMID 39990663, 2025). "The overexpression of HMMR in the mouse mammary epithelium influences the tumor microenvironment and cancer cell phenotype, leading to an increase in the genesis of Brca1-mutant tumors." (PMID 38576486, 2024). "In the context of LUAD, HMMR is highly expressed and has been shown to promote tumor cell proliferation, migration, and invasion while inhibiting apoptosis." (PMID 38293522, 2024). "The UALCAN, TIMER 2.0, and GEPIA2 analyses reveal a substantial upregulation of HMMR in tumor samples, indicating its role in disease progression." (PMID 38576486, 2024). "HMMR was overexpressed in tumour tissues, portal vein tumour thrombi (PVTT), and metastatic lymph nodes (MLN)." (PMID 38633247, 2024). "The tumour-promoting roles of HA are linked to its interaction with two main receptors, CD44 and HMMR (RHAMM)." (PMID 37673961, 2023). "We also found that while HMMR (encodes RHAMM) gene expression was robustly increased in NEPC tumors, only a subset of the tumor cells were positive for RHAMM protein expression." (PMID 37546702, 2023). "Initially, due to the positive nuclear expression of tumor cells, the study of hMMR protein expression was attached to the group of pMMR tumors; however, it was released as a separate group later." (PMID 36984490, 2023). "In present study, we found that HMMR accelerated cell cycle transition and promoted tumour growth via regulating CDK4/6 and p21." (PMID 36750558, 2023). "Our study of HMMR expression in pan-cancer found that HMMR was upregulated in most tumor types compared to normal tissues." (PMID 36704516, 2022). "HMMR overexpression in mouse mammary epithelium increases Brca1-mutant tumorigenesis by modulating the cancer cell phenotype and tumor microenvironment." (PMID 35393420, 2022). "Elevated HMMR in mouse mammary epithelium enhances the rate of Brca1-mutant carcinogenesis as it is involved in modifying the phenotype of tumor cell and tumor microenvironment." (PMID 36199789, 2022). "As a target gene of mir-34A-5p, HMMR can promote tumor growth in LUAD through the HCG18/Mir-34A-5p/HMMR axis." (PMID 35692818, 2022). "Hyaluronan-mediated motility receptor (HMMR) is highly related to the tumor process because of hyaluronan-mediated signaling." (PMID 36052378, 2022). "In the future, we will pay more attention to the function of HMMR in tumor metastasis and the tumor microenvironment regulation of LUAD." (PMID 35311097, 2022). "Consistently, the staining of Ki67 in isolated tumor nodules revealed that silencing of HMMR significantly suppressed the potential of tumor proliferation." (PMID 36002694, 2022). "In conclusion, we finally identified five genes most associated with tumor progression and prognosis: VRK1, NUP37, HMMR, SPC25, and RUVBL1." (PMID 36052378, 2022). "On the contrary, silencing of HMMR significantly decreased the disseminated tumor nodules in the peritoneal cavity." (PMID 36002694, 2022). "HMMR, a cell surface hyaluronan receptor and mitotic spindle protein and the driver of tumor progression, plays an important role in the modulation of motor activities and the maintenance of genome stability." (PMID 34126961, 2021). "Hyaluronic acid-mediated motility receptor (HMMR), a tumor-related gene, plays a vital role in the occurrence and progression of various cancers." (PMID 34527588, 2021). "T cells modified to express HMMR-specific TCRs were able to recognize AML target cells in a humanized xenograft mouse model leading to reduced tumor burden." (PMID 34572745, 2021). "An expressional study has been performed on the levels of HMMR protein expressions in GC patients and showed positive expression in cellular mucosa and cytoplasm in tumor cells, while it was expressed rarely in normal gastric mucosa." (PMID 32467737, 2020).
tumor (continued). "Compared with the control groups, knockdown of HMMR significantly suppressed HCC tumor growth in nude mouse." (PMID 33061798, 2020). "HMMR not only regulates tumor cell proliferation and invasion, but also affects centrosome structure and regulates mitotic spindle formation." (PMID 29152086, 2017). "CD44 and Hyaluronan Mediated Motility Receptor (RHAMM) are the two major cell surface proteins HA bind to trigger downstream signaling which promotes tumor growth and metastasis." (PMID 27595989, 2016). "Hyaluronan exerts its tumor promoting activity by binding to cell-surface receptor, in particular the hyaluronan-mediated motility receptor (HMMR)." (PMID 26180600, 2015). "In contrast, the expression levels of c-Myc target genes encoding proteins involved in cell proliferation (i.e. EMP1, HMMR) are more expressed in the stationary core subpopulations of GBM specimens as compared to their matched tumor rim." (PMID 23967279, 2013). "Thus, the hemizygous loss of HMMR/RHAMM, or silencing its expression in 2884 cells with genomic amplification of 5q, may relax this negative feedback mechanism, augment kinase activity, and sensitize tumour cells to AKI." (PMID 23328114, 2013). "In HCC, HMMR was reported to might be a potential target owe to its regulation of autophagy in tumour progression." (PMID 40845073, 2025). "Moreover, IHC analysis of LUAD specimens from the same source further confirmed the coordinated upregulation of both PSMD14 and HMMR in tumor tissues compared to adjacent normal regions." (PMID 41488674, 2025). "This increase in HMMR expression in tumor tissues suggests that an m6A-binding protein may positively regulate HMMR through methylation." (PMID 39990663, 2025). "HMMR could thus form an unrecognised signaling hub in these tumour cells, opening avenues for future prognostic or therapeutic investigation." (PMID 41253884, 2025). "In the context of cancer, HMMR and STAB2 have been implicated in tumor progression and metastasis." (PMID 40567905, 2025). "In addition, HMMR was involved in the regulation of the tumour immune microenvironment via immune cell infiltration and intercellular interactions." (PMID 38633247, 2024). "Hyaluronan-mediated motility receptor (HMMR) plays a crucial role in tumor progression." (PMID 38838151, 2024). "In addition, it was significantly associated with adverse clinical features and prognosis, while HMMR knockdown significantly inhibited the invasion ability of LUAD tumor cells." (PMID 36447119, 2023). "Importantly, by analysing tumour size and volume, we found that rapamycin significantly inhibited the proliferation of HMMR overexpressed tumour-bearing mice." (PMID 36750558, 2023). "Recent research suggests that the hyaluronan-mediated motility receptor (HMMR) could be a novel potential tumor prognostic marker." (PMID 36750807, 2023). "Upregulated HMMR notably accelerated tumour growth, and rapamycin alone inhibited tumour growth." (PMID 36750558, 2023). "However, the potential molecular mechanisms of HMMR in tumor growth and metastasis need to be explored in further studies." (PMID 35311097, 2022). "Furthermore, HMMR silencing suppresses GSC-derived tumor growth and extends the survival of mice bearing GSC xenografts." (PMID 35311097, 2022). "HMMR was previously found to modulate the tumor microenvironment." (PMID 35311097, 2022). "Considering the vital role of AKT signaling in cell–cell interaction and tumor proliferation, we next investigate whether HMMR function through activating AKT signaling." (PMID 36002694, 2022). "In addition, T-cell receptor-engineered T-cell therapy of HMMR efficiently inhibitor tumor growth in an animal model." (PMID 33763352, 2021). "Considering that HMMR can be expressed on the tumor surface, CAR-T targeting of HMMR could also be a future treatment strategy." (PMID 33763352, 2021).
tumor (continued). "Enrichment analysis indicated that HMMR might act as an oncogenic factor by regulating the EMT of tumor cells and suppressing adaptive immunity by promoting the infiltration of Th2 cells." (PMID 33763352, 2021). "Furthermore, HMMR promotes HCC tumor growth by activation of cell cycle progression, accompanied by changes in expression of cell cycle regulators." (PMID 33061798, 2020). "Next, the effect of HMMR knockdown on HCC tumor growth in nude mice was investigated." (PMID 33061798, 2020). "HMMR is an intracellular HA binding protein belonging to the microtubule-associated protein (MAP) family which is associated with microfilament formation and cell movement in tumor cells." (PMID 32467737, 2020). "Upregulated CAF-derived versican can subsequently enhance cancer cell motility and invasion by activating the nuclear factor-κB (NF-κB) signaling pathway and inducing the expressions of CD44, MMP-9, and hyaluronan-mediated motility receptor (HMMR) in the surrounding tumor microenvironment." (PMID 30568223, 2019). "In light of reports that suggest a role for HMMR (RHAMM) in tumor progression, we investigated whether RHAMM was contributory toward the endocrine-resistant phenotype of Tam-R and Fas-R cells." (PMID 27379207, 2016). "Our studies indicate that hemizygous loss of HMMR/RHAMM, which occurs in approximately 50% of aggressive MPNST, may oncogene-addict tumours to AURKA activity and sensitize these cancers to AKI." (PMID 23328114, 2013). "Moreover, HMMR's interaction with low molecular weight hyaluronic acid (HA) fragments notably enhances immune cell recruitment and exacerbates patient prognosis by activating tumor microenvironment dynamics and influencing pathways such as CD44 expression." (PMID 38740918, 2024). "Additionally, HMMR depletion markedly suppressed tumour growth." (PMID 36750558, 2023). "Additionally, analysis of clinical samples revealed that HMMR was overexpressed in tumour tissues." (PMID 36750558, 2023). "Interaction between HA and its receptors, CD44 and HMMR, participates throughout the course of cancer progression and metastasis including cancer cell proliferation, adhesion, migration, differentiation and stem cell maintenance, thus playing an important role in tumor development and metastasis." (PMID 36002694, 2022). "Furthermore, HMMR has been identified as a promising target for antibody therapy to block the extracellular function of HMMR on the surface of tumor cells, which might be a potential prognostic marker or therapeutic target against the disease." (PMID 34126961, 2021). "The receptor for hyaluronic acid-mediated motility (RHAMM/HMMR/CD168) is considered an interesting target for cancer immunotherapy, because it is a TAA expressed by a broad variety of hematological malignancies and solid tumors which is linked to tumor progression and has prognostic relevance." (PMID 27659531, 2016). "CDC25C, HMMR, and PRR11 exhibited focal areas of increased expression, indicating spatial variation in functional states within the tumor." (PMID 41602397, 2026). "Tumor-suppressor genes, including APC, BARD1, HMMR (RHAMM), KLLN, LZTR1, MCPH1 (BRIT1), MLH1, NF1, RB1CC1 (FIP200), SLC22A18, and SPTBN1, have been found to increase the risk of disease and tumor development." (PMID 40941673, 2025). "FIGNL1 has also been shown to promote the growth of tumour tissues and HCC cell lines by re‐establishing HMMR‐mediated ECM‐receptor interaction." (PMID 39428564, 2024). "A significant increase in UCK2, HMMR, and MAGEA6 expression and a significant decrease in CXCL8, EPO, PPARGC1A, FTCD, and CFHR3 expression was observed in tumor tissues." (PMID 38694506, 2024). "HMMR expression was up-regulated in LUAD, and its high expression was correlated with tumor size and lymph node metastasis." (PMID 36447119, 2023).
tumor (continued). "Herein, we investigate the function of one such gene, hyaluronan-mediated motility receptor (HMMR), and the therapeutic potential of targeting HMMR to sensitise tumour cells to enzalutamide." (PMID 37673961, 2023). "The expression of UBE2S, HMMR and KRT6A expression in tumor tissues was substantially higher than that in adjacent non-cancerous tissues." (PMID 37199651, 2023). "To further verify the results of bioinformatics analysis, we applied qRT-PCR to validate the mRNA levels of HMMR, SPP1, FN1, CCNB1, CXCL8, MAD2L1 and CCNA2 in 10 paired tumor and adjacent normal tissues with qRT-PCR." (PMID 34126961, 2021). "Consistent with the transcriptome data, the protein expression of 4 genes (IGF2BP1, IGF2BP3, HMMR and ADAMTS12) were up-regulated in LUAD tumor samples." (PMID 34721973, 2021). "HMMR promotes the proliferation of HCC cells in vitro by activating G1/S and G2/M checkpoint transformation, and knockdown of HMMR suppresses HCC tumor growth in nude mice." (PMID 33974527, 2021). "HA receptors (especially CD44, hyaluronan-mediated motility receptor RHAMM, lymphatic vessel endothelial hyaluronic acid receptor 1 LYVE1) are activated in cancer cells to promote cell infiltration and tumor malignancy." (PMID 33613290, 2021). "Hyaluronan-mediated motility receptor (HMMR) promotes HA uptake, and related time to biochemical failure in Gleason score 7 tumor." (PMID 32266115, 2020). "In MCF-7 cell lines, combination therapy enhanced the downregulation of essential components of the cell cycle (HMMR, AURKB, BIRC5) that control proliferative activities and tumour growth alongside downregulation of the anti-senescence markers FOXM1 and E2F1." (PMID 32787886, 2020). "In this study, we found that HMMR acts as an oncogene activating HCC cell cycle progression and promoting HCC cell proliferation in vitro and tumor growth in vivo." (PMID 33061798, 2020). "Additional studies predict that the pro-tumor functions of HA also depend upon the display of specific receptors, notably the injury-related HA receptor, RHAMM (gene name HMMR), which activates oncogenic signaling pathways." (PMID 29868579, 2018). "Immunohistochemical staining assay was used for xenograft tumor tissue staining of Ki-67, CD31 and HMMR." (PMID 29152086, 2017). "HA has been shown to influence cell behavior during embryonic development and tumor development by interacting with cell-surface receptors such as the type I transmembrane protein CD44 and hyaluronan-mediated motility receptor (HMMR)." (PMID 28207787, 2017). "HA fragments are pro-inflammatory and activate signaling pathways that promote survival, migration, and invasion within both tumor and host cells through binding to HA receptors such as CD44 and RHAMM/HMMR." (PMID 26106384, 2015). "CDK1, HMMR, PTTG1, and TTK were positively correlated with tumor-infiltrate lymphocytes, which might involve tumor immune response." (PMID 34187556, 2021). "HMMR acts as an oncogene of LUAD and induces tumor progression." (PMID 34956315, 2021). "Hyaluronic acid (HA) is a nonsulfated glycosaminoglycan that along with its family members composed of HA receptors (CD44, cluster of differentiation antigen 44; RHAMM, hyaluronan-mediated motility receptor), HA synthases (HAS1, HAS2, HAS3), and hyaluronidases, promotes tumor growth and progression." (PMID 33958632, 2021). "HMMR acts as an essential component during the polo-like kinase 1 (PLK1)-dependent mitotic spindle positioning pathway, which is required for neural development, neonatal survival, and tumor formation." (PMID 33061798, 2020). "Silencing of HMMR reduces HCC cell proliferation in vitro and tumor growth in vivo." (PMID 33061798, 2020). "Interestingly, our data on exosomal protein profiles from treated Caco-2 showed an enrichment of upregulated proteins involved in tumor etiopathogenesis, including CRC (CD59, CRP, CTSD, HMMR, LY6K, TRIM22), and in cell cycle control (BRAF, CDC2, ERBB2)." (PMID 25594007, 2014).